XCR1 (X-C motif chemokine receptor 1)
Diseases named in the same sentence as XCR1 in open-access papers (continued):
Sharing a sentence is not in itself a finding about the gene and the disease.
ovarian carcinoma (1 paper, 2013). A malignant neoplasm originating from the surface ovarian epithelium. "Chemokines lymphotactin 1 and lymphotactin 2, XCL1 and XCL2, respectively, bind and activate XCR1, leading to increased proliferation and migration of ovarian cancer cells that express XCR1." (PMID 24384839, 2013). "Our group has recently shown that the lymphotactin receptor XCR1, the only member of the C family of chemokine receptors plays an important role in metastatic development of ovarian cancer." (PMID 24384839, 2013). "The ovarian carcinoma cells themselves express XCL1, and XCL2 is detected in the ascites from ovarian carcinoma, suggesting that XCL/XCR1-driven cell proliferation and migration could contribute to growth and expansion of peritoneal metastasis." (PMID 24384839, 2013).
ovarian tumors (1 paper, 2023). "In ovarian tumors, XCR1 was expressed in the majority (~80%) of BDCA3+ cDC1s, suggesting enrichment of XCR1+ cDC1s in tumors and possibly, an enrichment of a more mature cDC1 DC population since Clec9a and BDCA3 are reported to also be expressed in pre-DCs, while XCR1 was not." (PMID 37942313, 2023).
paraganglioma (1 paper, 2023). A benign or malignant neoplasm arising from paraganglia located along the sympathetic or parasympathetic nerves. "It was found that XCR1 and CXCL9 have a significant positive correlation in a variety of tumors, including THCA, SKCM, SARC, KIRC, TGCT, BRCA, PCPG (pheochromocytoma and paraganglioma), and KIRP." (PMID 37895310, 2023).
peripheral nerve injury (1 paper, 2021). Injury to a peripheral nerve. "This study identified a novel role for XCL1/XCR1 in nociceptive processing and suggests a pronociceptive role for the XCL1/XCR1 axis in peripheral nerve injury and neuropathic pain." (PMID 35295531, 2021).
pneumonia (1 paper, 2022). An acute, acute and chronic, or chronic inflammation focally or diffusely affecting the lung parenchyma, caused by an infection in one or both of the lungs (by bacteria, viruses, fungi, or mycoplasma.). "Increased transcription of chemokine receptors CCR2 (CCL2/monocyte chemoattractant protein-1 (MCP-1) receptor) and CCR5 (CCL3/MIP-1A receptor) were observed, indicating that these inflammatory signals were activated, but receptors XCR1, CCR4, and ACKR3 were downregulated in the pneumonia group." (PMID 36119044, 2022).
polyposis (1 paper, 2024). "Our analysis revealed distinct patterns: XCR1, CXCL13, and CXCR6 expression levels were diminished in M1-staged and advanced CRC cases, while CXCR6 expression was elevated in CRC patients with a history of polyposis, and CCR10 expression was heightened in lympho-invasive CRC." (PMID 39835121, 2024).
pulmonary sarcoidosis (1 paper, 2022). Sarcoidosis affecting the lung parenchyma. "We indeed found that essentially all of the IL12B expression was from a similar population of IRF8+XCR1+BATF3+ cDC1s in pulmonary sarcoidosis." (PMID 35668129, 2022).
rectum adenocarcinoma (1 paper, 2023). An adenocarcinoma arising from the rectum. "However, compared with adjacent normal tissue, an even lower expression of XCR1 was observed in most cancers (Kruskal–Wallis test p < 0.05), such as LIHC, LUAD, LUSC, READ (rectum adenocarcinoma), THCA, UCEC, and HNSC." (PMID 37895310, 2023).
renal carcinoma (1 paper, 2023). A carcinoma arising from the epithelium of the renal parenchyma or the renal pelvis. "The results above suggest that XCR1 genes downregulation inhibited renal cancer cell proliferation, migration, and EMT." (PMID 37816979, 2023).
renal cell carcinoma (1 paper, 2020). "In renal cell carcinoma, a study reported that a higher expression of genes related to cross-presenting DCs, including XCR1, was associated with better survival of patients treated with PD-L1 blockade." (PMID 32457745, 2020). "In the same study, a DC gene signature (including XCR1, BATF3, FLT3, and IRF8) expression correlated with increased survival of patients treated with PD-L1 blockade in NSCLC and renal cell carcinoma." (PMID 32457745, 2020).
schistosomiasis (1 paper, 2022). An infectious disease caused by parasitic trematodes of the genus Schistosoma that colonize human blood vessels and release eggs that can cause granulomatous reactions leading to acute (swimmer's itch or acute schistosomiasis syndrome) or chronic disease. "C108 has clear splenic cDC1 phenotype, high CD24 and XCR1, and relatively high CD86, and has clearly distinct group-wise effects: enriched after exposure to maternal schistosomiasis, but relatively reduced after exposure to treatment." (PMID 35833137, 2022).
skin cancer (1 paper, 2023). "Our results show that a marked correlation between the CD103+DC signature (IRF8, FMS‐like tyrosine kinase 3 ligand, CLEC9A, CLNK, XCR1, BATF3, and ZBTB46) and chemokines C‐X‐C motif chemokine ligand 9, CXCL10, and CD8A in a mouse model with DMBA/TPA‐induced skin cancer." (PMID 36891351, 2023).
T cell deficiency (1 paper, 2016). "The findings indicate that the T cells present in XCR1-DTA mice were not defective in proliferation, but were more prone to undergo cell death, likely contributing to the T cell deficiency observed in these mice." (PMID 27005831, 2016).
toxoplasmosis (1 paper, 2022). A parasitic disease contracted by the ingestion or fetal transmission of toxoplasma gondii. "We have extended our previous studies of Bcl3 in toxoplasmosis by assigning a specific role in Xcr1+ cDC1 cells for antigen presentation and CD8+ T cell activation, possibly resulting from Bcl3-dependent effects on antigen cross presentation." (PMID 36318581, 2022).
triple-negative breast carcinoma (1 paper, 2020). An invasive breast carcinoma which is negative for expression of estrogen receptor (ER), progesterone receptor (PR), and human epidermal growth factor receptor 2 (HER2). "It was reported that the overexpression of X-C motif chemokine receptor 1 (XCR1), a specific receptor for chemokine X-C motif chemokine ligand 1 (XCL1), stimulates the migration of MDA-MB-231 triple-negative breast cancer cells." (PMID 33374849, 2020).
tumor (131 papers, 2013 to 2026). "Alginate formed an in situ gel at the physiological Ca2+ concentration in tumors, and the release of XCL‐1 chemokines attracted XCR‐1+ DCs into tumors, promoting cross‐presentation of tumor‐associated antigens by the tumor‐infiltrated DCs." (PMID 41287898, 2025). "Xcr1 deletion increased tumor size and caused a significant reduction in intratumoral cDC1 frequency and number." (PMID 35393950, 2022). "In XCR1-deficient mice, tumour growth inhibition by XCL1-OT-I plus poly(I:C) was abolished in both prophylactic and therapeutic models." (PMID 32066911, 2020). "Furthermore, CXCR2 and XCR1 are associated with the metastatic potential at the forefront of tumor invasion." (PMID 41445742, 2025). "To assess whether H2-Aa–deficient cDC1 mediated the tumor suppressive effect observed in H2-Aacit/cit mice, we utilized an Xcr1-cre driver that is largely restricted to the cDC1 lineage." (PMID 39470607, 2024). "As the XCR1+ DCs (cDC1) are linked to the anti-tumor activation of cytotoxic CD8+ T cells, this may explain the higher levels of CD8+ TILs in the treated tumor samples." (PMID 36915084, 2023). "Among the CD11b+ myeloid cells, we identified cDCs and macrophages based on known markers that have been previously identified in human tumor-infiltrating immune cells, including tumor-associated dendritic cells (XCR1+ cDC1, SIRP1a+ cDC2, SiglecH+ pDC) and tumor-associated macrophages (TAMs)." (PMID 37055410, 2023). "Mammalian XCR1+ cDCs excel at cross-presentation of viral and tumour cell-associated antigens." (PMID 37954617, 2023). "Importantly, these two chemokines are extensively accepted to recruit XCR1+ cross-presenting DCs into the tumor to cause tumor-driving inflammation, thus changing a “cold tumor” into a “hot tumor”." (PMID 37675100, 2023). "Our analyses showed that CD8+ T cells, which are directly associated with tumor immunotherapy response, as well as T cells were more highly expressed at higher levels of all four molecules; B cells were also more highly expressed at higher levels of XCR1, CCR10, CXCL13, CXCR6." (PMID 39835121, 2024). "Tumor infiltration by XCR1+ conventional dendritic cells (cDC1) correlates strongly with favorable prognosis and improved responses to immunotherapy." (PMID 41469380, 2025). "Mechanistically, Tal-PDT enhanced the induction of XCR-1+ dendritic cells in the proximal draining lymph node likely through the induction of ferroptosis in tumor cells." (PMID 39842944, 2025). "This indicates that ferroptosis of cancer cells enhanced the generation of XCR-1+ cDC1s and stimulated Tpex cells in the proximal dLN, which then circulated systemically to the opposite tumor site." (PMID 39842944, 2025). "This combination therapy notably increased the activation of XCR1+ dendritic cells and the number of CD8+ T cells in the tumor, both of which are associated with anti-tumor immunity." (PMID 40573881, 2025). "NK cell-derived XCL1 has been strongly implicated in the direct recruitment and activation of Clec9a+XCR1+ cDC1s into solid tumors, with cDC1s being essential for tumor antigen cross-presentation in tumor-draining lymph nodes." (PMID 40410571, 2025). "Whereas, the amount of DCs (CD11c+ MHC IIhigh F4/80−) within the tumor decreased, we found that the frequency of the cross presenting XCR1+ subtype of DCs within the DC population was obviously higher in tumors treated with Ad5/11-αCD3TAT-Trimer." (PMID 39789356, 2025). "Although intestinal cDC subsets are commonly classified using XCR1 and SIRPα, our analysis revealed that tumor-infiltrating cDC are rather heterogeneous with respect to the expression of these markers." (PMID 38500875, 2024). "The results showed that, with the exception of SMIM24, which was highly expressed in normal tissues, PLCB2, HLA-DQB2, IFNG, and XCR1 were all highly expressed in tumor tissues." (PMID 39273185, 2024).
tumor (continued). "In this study, we specifically targeted XCR1, expressed on the surface of cDC1, and the DNA vaccine that fused its ligand-XCL1 with two tumor-associated antigens showed stronger immunogenicity and antitumor effects in mice." (PMID 38339158, 2024). "We found that Xcl1 and Xcr1 that control cDC1 migration were notably upregulated in tumors from hsBCL9z96-treated CT26 tumor-bearing mice." (PMID 38811552, 2024). "We previously showed that Batf3 + Xcr1 + cDC1s are required to not only prime tumor-specific CD8 T cells in the spleen, but also maintain adoptively transferred Klrg1 + effector T cells in both spleen and tumor." (PMID 36472588, 2023). "The development of cytotoxic CD8+ T lymphocytes requires antigen cross presentation by XCR1+ cDC1 cells and tumor-infiltrating potential, a program driven by type 1 cytokines such as IL12 and IFNγ." (PMID 37833072, 2023). "XCR1+ cDC1s play a key role in cross-presenting tumor antigens on MHC I to activate antitumoral cytotoxic T cells, and mature LAMP3-high DCs in our dataset had the highest expression of CD80/CD86 costimulatory signals needed to fully activate T cell responses." (PMID 37433281, 2023). "A gating strategy that utilized the restricted expression of XCR1 in CD8+ cDC1s in the spleen and CD103+ cDC1s in the tumor was adopted to evaluate XCR1 RO and IFN activity in cDC1s following treatment." (PMID 37942313, 2023). "Of interest, tumor cDC1s were approximately 90% positive for XCR1 and XCR1 appeared to have increased expression in cDC1s (by MFI) in tumors compared to spleen in both B16 and MC38 tumor-bearing mice." (PMID 37942313, 2023). "In contrast to XCR1, surface expression of Clec9a was undetected in the human dissociated tumor samples, likely due to Clec9a sensitivity to clipping from enzymatic digestion based on loss of Clec9a expression in PBMCs treated with Collagenase." (PMID 37942313, 2023). "For example, in human, CD103+ TRM cells can produce granzyme B (GZMB) and IFN-γ, which can enhance recruitment of monocytes, NK cells, and XCR1+ cDC1 to the tumor site, resulting in anti-tumor." (PMID 38130725, 2023). "Taken together, we highlight the successful application of the Cyclone pipeline on multiplexed imaging data in tumor tissue to discriminate two different XCR1+ subsets and their spatial features within the tumor microenvironment." (PMID 37731497, 2023). "Clustering of the tumor microenvironment imaging data revealed a CD163+XCR1+ cell subset that was enriched in the stroma region." (PMID 37731497, 2023). "Xcr1DTR/DTR mice provide an opportunity to study the role of Xcr1 signaling in cDC1s, which we find to promote cDC1 accumulation in tumor-bearing hosts, whereas Xcr1DTR/– mice can specifically target cDC1s with at least 1 allele of Xcr1." (PMID 35393950, 2022). "Here, we found that combination therapy induced a significant increase in XCR-1 expression on cDC1 on both sides of tumor, indicating the presence of functional DCs." (PMID 36513720, 2022). "Taken together, these results show that targeting of XCR1 increases tumor antigen uptake by cDC1s, resulting in an improved CD8+ T cell activation." (PMID 35428705, 2022). "Next, work with a novel Xcr1-Cre strain was used to test the specific interactions involving cDC1 that occur during tumor rejection." (PMID 34480145, 2022). "First, the conditional deletion of all MHC-I molecules from cDC1, using Xcr1-Cre crossed with a floxed allele of β2 microglobulin, confirmed the expected peptide: MHC interactions with CD8 T cells in tumor rejection." (PMID 34480145, 2022). "To the best of our knowledge, we show for the first time the potential of targeting XCR1 on peripheral blood human cDC1s for inducing antigen-specific CD8+ T cell responses to a tumor antigen." (PMID 35428705, 2022). "A recent publication also emphasized that delivery of type I interferon elicited an anti-tumor immunity via XCR1+ dendritic cells." (PMID 35145233, 2022).
tumor (continued). "The IHC staining results of the 36 clinical samples also showed that the expression of XCR1 was significantly higher in tumor tissues compared with that in normal tissue." (PMID 33377624, 2021). "In particular, recently characterized cross-presenting dendritic cells are capable of inducing CD8+ cytotoxic T-lymphocytes against exogenous antigens such as tumor antigens and uniquely express the chemokine receptor XCR1." (PMID 34065346, 2021). "Here we establish that cross-presenting XCR1+ DCs are essential for enhanced priming of tumor-specific CD8+ T cells during vaccination with IFNβ." (PMID 34552594, 2021). "X‐C motif chemokine receptor 1 (XCR1) exerts important roles in tumor progression; however, its role in ccRCC is unclear." (PMID 33377624, 2021). "These DCs broadly comprise the cross-presenting DC subset (specifically the XCR1+ DC population) and have been shown to be crucial in mediating effective anti-tumor responses." (PMID 34552594, 2021). "The IHC of XCR1 showed to be membrane positive and gradually increased from stage I to IV; moreover, its expression in the tumor of grade I is very weak or invisible, while that in grade II to IV is much stronger." (PMID 33377624, 2021). "We and others have demonstrated previously that XCR1+ cross-presenting DCs are the key cell type cross-priming anti-tumor CD8+ T cell immunity." (PMID 34552594, 2021). "Other approaches have been assessed in a few clinical trials, such as increasing the expression of XCL1 within the tumor in order to recruit CD141+ XCR1+ DCs." (PMID 32075343, 2020). "In MDA-MB-231 cells, XCR1 overexpression inhibited tumor cell growth in vitro and tumorigenesis in vivo and promoted cell migration and invasion." (PMID 33374849, 2020). "Taken together, these data indicate that hetIL-15 treatment promotes the production of the chemokine XCL1 by intratumoral lymphocytes leading to increased tumor infiltration by CD103+XCR1+IRF8+ cDC1." (PMID 32461349, 2020). "The tolerogenic DCs expressing down-regulated XCR1+CD141+ appear to be induced by tumor-derived soluble factors or dexamethasone, while the immunogenic DCs usually express XCR1+CD141+ molecules with a cross-presentation function in humans." (PMID 31531696, 2019). "Cross-presenting Xcr1+CD8α DCs are attractive APCs to target for therapeutic cancer vaccines, as they are able to take up and process antigen from dying tumor cells for their MHCI-restricted presentation to CD8 T cells." (PMID 30863405, 2019). "During the same year, another study has targeted Xcr1+CD103+ DCs via laser-assisted intradermal ear vaccination with Xcl1-OVA fusion protein on day 3 post tumor graft." (PMID 30863405, 2019). "Among the top 5 degree genes, 2 DEGs (IL10 and XCR1) were highly relative to clinical outcome of ccRCC patients as well as the infiltration of tumor immune cells." (PMID 31781309, 2019). "The percentage of XCR1+ DCs was increased in the tumor of mice treated with LTX-315+RT compared to mice treated with saline, LTX-315 alone or RT alone (8.4±2.4% in LTX-315+RT (p<0.05) v." (PMID 30400822, 2018). "For example, CD123+ pDCs were found to selectively express CCR2, CMKLR1, and CXCR3, receptors known to be involved in DC maturation, trafficking and recruitment at tumor sites whereas XCR1 and CX3CR1, were selectively expressed by CD141+ mDCs and CD1c+ mDCs." (PMID 29795118, 2018). "Recruitment of XCR1+ dendritic cells (DCs) to the tumor is critical for priming of anti-tumor CD8+ T cells following induction of ICD, and this process can be regulated by natural killer (NK) cells." (PMID 30400822, 2018). "cDC1s are also characterized by their high expression of XCR1 and have been reported to play predominantly an anti-tumor role." (PMID 30345015, 2018). "We also show that this axis can be subverted by tumor-derived PGE2, which both impairs NK cell function and causes downregulation of the XCR1 and CCR5 chemokine receptors on cDC1." (PMID 29429633, 2018).